TIMM8A (translocase of inner mitochondrial membrane 8A)
Description:
Mitochondrial intermembrane chaperone that participates in the import and insertion of some multi-pass transmembrane proteins into the mitochondrial inner membrane. Also required for the transfer of beta-barrel precursors from the TOM complex to the sorting and assembly machinery (SAM complex) of the outer membrane. Acts as a chaperone-like protein that protects the hydrophobic precursors from aggregation and guide them through the mitochondrial intermembrane space. The TIMM8-TIMM13 complex mediates the import of proteins such as TIMM23, SLC25A12/ARALAR1 and SLC25A13/ARALAR2, while the predominant TIMM9-TIMM10 70 kDa complex mediates the import of much more proteins. Probably necessary for normal neurologic development.
Synonyms: DDP; DDP1; MTS; DFN1; TIM8
Tractability: Antibody: UniProt places it where antibodies can reach, with high confidence. PROTAC: ubiquitination databases record sites on it; its protein half-life has been measured.
Gene: Protein-coding gene on chromosome X (101,345,652 to 101,349,001, reverse strand). Ensembl gene ENSG00000126953.
Subcellular location: Mitochondrion inner membrane
Subcellular location (Human Protein Atlas): Mitochondria
Pathways (Reactome):
Protein localization: Mitochondrial protein import
Gene Ontology:
Molecular function: identical protein binding; protein binding; zinc ion binding
Biological process: protein insertion into mitochondrial inner membrane; nervous system development; protein localization to mitochondrion
Cellular component: mitochondrial intermembrane space; mitochondrial intermembrane space chaperone complex; mitochondrion; mitochondrial inner membrane
Gene-disease validity (ClinGen):
ClinGen rates the evidence that TIMM8A causes each of these diseases.
deafness dystonia syndrome (X-linked): Definitive. An X-linked recessive neurodegenerative syndrome characterized by clinical manifestations commencing with early childhood onset hearing loss, followed by adolescent onset progressive dystonia or ataxia, visual impairment from early adulthood onwards and dementia from the 4th decade onwards.
Homologues: Orthologues: chimpanzee TIMM8A (100% identical), macaque TIMM8A (100% identical), rabbit TIMM8A (100% identical), guinea pig TIMM8A (98% identical), pig TIMM8A (98% identical), mouse Timm8a1 (95% identical), rat Timm8a1 (95% identical), zebrafish timm8a (72% identical), tropical clawed frog TIMM8A (69% identical), dog TIMM8A (66% identical). Paralogues in human: TIMM8B (39% identical).
Diseases named in the same sentence as TIMM8A in open-access papers:
TIMM8A is named in the same sentence as 59 diseases in open-access papers, as found by Europe PMC text mining. Sharing a sentence is not in itself a finding about the gene and the disease. The quoted sentences say what the papers report.
Mohr-Tranebjaerg syndrome (18 papers, 2010 to 2025). "For example, Mohr-Tranebjaerg syndrome (linked to TIMM8A mutations) is marked by severe neurodegenerative symptoms, particularly dystonia and motor dysfunction, accompanied by iron accumulation in the basal ganglia." (PMID 40597358, 2025). "Here we report a novel TIMM8A mutation (c.98_101dupAGCA; p.Leu35fs) associated with Mohr-Tranebjaerg syndrome (MTS), presenting with progressive dystonia and iron accumulation in the basal ganglia." (PMID 40597358, 2025). "Mohr-Tranebjaerg syndrome (MTS) is a rare X-linked recessive neurodegenerative disorder caused by pathogenic variants in the TIMM8A gene." (PMID 40597358, 2025). "Large deletions involving BTK and adjacent genes, such as TIMM8A, cause syndromic forms, such as Mohr-Tranebjaerg syndrome, which includes neurodegeneration and hearing loss." (PMID 40863427, 2025). "For example, mutations in TIMM8A have been found in patients suffering Mohr-Tranebjaerg syndrome/deafness dystonia syndrome." (PMID 37129366, 2023). "Deafness-dystonia-optic neuronopathy syndrome is a rare neurodegenerative disease induced by a mutation in the TIMM8A gene encoding the IMS protein DDP1." (PMID 36090790, 2022). "Mohr-Tranebjaerg syndrome (DYT-TIMM8A) is an X-linked recessive syndrome caused by mutations in the nuclear gene TIMM8A, encoding for a protein involved in mitochondrial transport." (PMID 35207493, 2022). "TIMM8A is an X-linked gene that is associated with deafness, dystonia, optic neuronopathy, and Mohr-Tranebjaerg syndrome." (PMID 33426505, 2020). "Mohr-Tranebjaerg syndrome (MTS) is a rare X-linked recessive neurodegenerative disorder caused by mutations in the Translocase of Inner Mitochondrial Membrane 8A (TIMM8A) gene, which encodes TIMM8a, a protein localized to the mitochondrial intermembrane space (IMS)." (PMID 40075073, 2025). "TIMM8A mutations are linked to the Mohr-Tranebjaerg syndrome, a progressive neurological illness." (PMID 36248992, 2022). "One novel hemizygous mutation, c.201delT (p.E68Sfs*11) in TIMM8A, was identified in a male proband D211 as a likely pathogenic mutation since similar truncating mutations p.E24* and p.R80* in TIMM8A have been reported to cause hearing loss associated with Mohr-Tranebjaerg syndrome." (PMID 31992338, 2020). "Mohr-Tranebjaerg syndrome (MTS), also known as deafness-dystonia-optic neuropathy syndrome, is a rare neurodegenerative disorder linked to mutations in the TIMM8A gene located on the X chromosome." (PMID 40597358, 2025). "TIMM8A (translocate of inner mitochondrial membrane 8a) has been found that TIMM8A is related to Mohr-Tranebjaerg syndrome and focal muscle Zhang Li disorder.The molecular functions include mitochondrial protein input and protein metabolism.TIMM8B is an important homologue of this gene." (PMID 36248992, 2022). "Thus, it is important for clinicians to consider the possibility of a deletion of the last exon 19 in the BTK gene in patients suspected of having DDON syndrome, and to further test for the existence of the neighboring TIMM8A gene to allow for an effective therapeutic strategy." (PMID 33013854, 2020). "The absence of hearing loss emphasizes the phenotypic variability in patients with Mohr-Tranebjaerg syndrome, and the normal biochemical findings rule out other potential diagnoses, such as Wilson’s disease, further reinforcing the link to mitochondrial dysfunction due to the TIMM8A mutation." (PMID 40597358, 2025). "Two patients with contiguous gene deletion syndrome (CGS) encompassing the TIMM8A/DDP1 gene presented with early-onset progressive post-lingual sensorineural Deafness, gradual Dystonia, and Optic Neuronopathy syndrome (DDON) or Mohr-Tranebjaerg syndrome (MTS)." (PMID 33013854, 2020).
deafness (12 papers, 2019 to 2025). An inherited or acquired condition characterized by the complete loss of the ability to hear from one or both ears. "Yeast TIM8 was initially identified as a homolog of human TIMM8A/DDP1, which is associated with human deafness–dystonia syndrome." (PMID 40001574, 2025). "When the DDP1/Timm8a-Timm13 complex assembly is defective, it can cause human deafness/dystonia syndrome." (PMID 36899394, 2023). "In other cases, these disorders also have a deafness component, for example in the case of TIMM8A, which is associated with deafness-dystonia-optic neuropathy syndrome." (PMID 33815052, 2021). "Located on Xq22, the gene associated with DDON syndrome, TIMM8A (originally called DDP for deafness–dystonia peptide; OMIM#300356) encodes a small protein that localizes to the intermembrane space in mitochondria." (PMID 31903733, 2020). "Importantly, a new variant of the TIMM8A chaperone known as small TIMM family was reported to cause deafness‐dystonia‐optic neuronopathy syndrome (DDON), highlighting the importance of these MLPs during neurodevelopment." (PMID 40842332, 2025). "TIM8A/DDP1 (Deafness Dystonia Peptide), encoded by the TIMM8A gene, is an intermembrane space mitochondrial microprotein associated to a rare disease called Mohr‐Tranebjaerg syndrome (MTS), also known as deafness‐dystonia‐optic neuronopathy (DDON)." (PMID 40842332, 2025). "The yeast gene TIM8 was initially identified as a homolog of human TIMM8A/DDP1, and mutation of the latter gene is associated with human deafness–dystonia syndrome." (PMID 40001574, 2025). "In the present study, we identified three novel TIMM8A variations in three Chinese families by applying targeted gene capture to 127 deafness-related genes combined with NGS, as well as a SNP array." (PMID 30634948, 2019). "We identified a novel frameshift variation in the TIMM8A gene in this Chinese family with auditory neuropathy, who visited the outpatient department for deafness genetic consultation, as typical auditory neuropathy was the only phenotype in the proband at this stage." (PMID 30634948, 2019). "Subsequently, a case report also analyzed the relationship between deafness/dystonia syndrome and DDP1/Timm8a-Timm13." (PMID 36899394, 2023).
Dystonia (12 papers, 2013 to 2025). An abnormally increased muscular tone that causes fixed abnormal postures. "In this report, we describe a novel TIMM8A variant in a male patient with progressive dystonia, motor coordination difficulties, and iron deposits in the basal ganglia, but notably without hearing impairment." (PMID 40597358, 2025). "Mohr–Tranebjaerg syndrome is caused by mutations in the TIMM8A gene, which is a rare X-linked recessive disorder resulting in early-onset hearing impairment, progressive visual deterioration, and gradual dystonia." (PMID 37217926, 2023). "Mutations in TIMM8A cause a neurodegenerative disease, Mohr-Tranebjærg syndrome (MTS), which is characterised by sensorineural hearing loss, dystonia and blindness." (PMID 31682224, 2019). "In line with this, mutations in the TIMM8A gene that encodes the hTim8a protein, cause Mohr-Tranebjærg syndrome (MTS), an X-linked recessive neurodegenerative disorder characterised by progressive sensorineural hearing loss, dystonia, cortical blindness and dysphagia." (PMID 31682224, 2019).
DDON syndrome (10 papers, 2013 to 2025). "TIMM8A located in Xq22 encodes a small protein located in the mitochondrial intermembrane space associated with Deafness-dystonia-optic neuronopathy (DDON syndrome) also called Mohr–Tranebjaerg syndrome (MTS)." (PMID 36570450, 2022). "Frameshifts or premature stops represent the majority of mutations in TIMM8A that cause DDON syndrome." (PMID 31903733, 2020). "We report a novel TIMM8A variant in a patient with DDON syndrome that alters the initiation codon and employed functional analyses to determine the significance of the variant and its impact on mitochondrial morphology." (PMID 31903733, 2020). "The rare, X‐linked neurodegenerative disorder, Mohr–Tranebjaerg syndrome (also called deafness‐dystonia‐optic neuronopathy [DDON] syndrome), is caused by mutations in the TIMM8A gene." (PMID 31903733, 2020). "Patients with DDON syndrome typically bear loss of function mutations in the TIMM8A gene, although some missense mutations have also been reported that impact the start codon." (PMID 31903733, 2020). "We report a novel TIMM8A variant in a patient with DDON syndrome that alters the initiation codon, resulting in no detectable protein and a reduction in TIMM8A transcript abundance." (PMID 31903733, 2020). "DDON syndrome results from mutations of a single gene, TIMM8A, and the novel variant described in this case report as a start loss located at the first codon may be a candidate for read through pharmaceuticals (Bello & Pegoraro, 2016; Keeling, Xue, Gunn, & Bedwell, 2014; Rowe & Clancy, 2009)." (PMID 31903733, 2020).
breast carcinoma (7 papers, 2015 to 2025). "Using logistic regression model, we illustrated the association between TIMM8A and clinicopathological factors in patients with breast cancer from TCGA." (PMID 35501914, 2022). "Functions of TIMM8A mutations and 50 genes significantly associated with TIMM8A mutations in breast cancer (BRCA) and uterine corpus endometrial cancer (UCEC) were analyzed by GO and KEGG in LinkedOmics database." (PMID 36207751, 2022). "The somatic mutation frequency of TIMM8A in breast cancer was 0.55% and was mainly composed of missense mutations." (PMID 36248992, 2022). "Next, the noncoding RNA (ncRNA)-associated regulation of TIMM8A, involving microRNAs (miRNAs) and circular RNAs (circRNAs), was also predicted in breast cancer." (PMID 35501914, 2022). "The diagnostic and prognostic role of TIMM8A in breast cancer was further evaluated." (PMID 36248992, 2022). "The mutation frequency of TIMM8A in breast cancer was evaluated in the cBioPortal database." (PMID 36248992, 2022). "Recent research demonstrates that TIMM8A functions as an oncogene in breast cancer and correlates positively with poor prognosis in breast cancer patients." (PMID 40918471, 2025). "After TIMM8A knockdown, breast cancer cells proliferation showed to be restrained, apoptosis increased." (PMID 35501914, 2022). "The mRNA expression levels of TIMM8A were significantly upregulated in patients with breast cancer based on TCGA and GTEx database." (PMID 35501914, 2022). "Most importantly, we verified the biological function of TIMM8A in different models in vivo and in vitro, which can promote tumor proliferation and act as an oncogene in breast cancer." (PMID 35501914, 2022). "In the current study, we performed the first-ever comprehensive analysis about the expressions, clinical values and biological functions for TIMM8A in breast cancer." (PMID 35501914, 2022). "To explore the relationship between TIMM8A expression and OS in breast cancer patients, we drew Kaplan Meier curves." (PMID 36248992, 2022). "To examine the mRNA and protein expression of TIMM8A in breast cancer, we analyzed the expression data of TIMM8A in TCGA." (PMID 36248992, 2022). "Then, the expressions of TIMM8A were compared in breast cancer samples and normal tissues in TCGA, GTEx and Human Protein Atlas database, indicating that TIMM8A was highly expressed in breast cancer tissues." (PMID 35501914, 2022). "The expression of TIMM8A in breast cancer tissues was significantly higher than that in normally adjacent tissues to cancer." (PMID 36248992, 2022). "Our results confirmed that ncRNAs-mediated upregulation of TIMM8A correlated with poor prognosis and act as an oncogene in breast cancer." (PMID 35501914, 2022). "Richardson’s study found that TIMM8A is highly expressed in breast cancer compared with normal tissues." (PMID 35501914, 2022). "To explore the relationship between TIMM8A mRNA expression and clinicopathological features in breast cancer tissues, we performed Mann-Whitney U test and logistic regression analysis." (PMID 36248992, 2022). "We found that TIMM8A showed higher expression level in breast cancer and the higher TIMM8A mRNA expression group had a poorer prognosis than the lower TIMM8A group." (PMID 35501914, 2022). "Paired data analysis also revealed that TIMM8A messenger RNA expression levels were significantly higher in breast cancer tissues (n = 112) than in adjacent normal tissues (n = 112) (3.351 soil 0.597 vs 2.998 soil 0.617, P < 0.001)." (PMID 36248992, 2022). "The OS of patients with breast cancer with high TIMM8A expression was shorter than that of patients with breast cancer with low TIMM8A expression (115.4 months vs. 148.5 months, P < 0.001)." (PMID 36248992, 2022). "Taken together, our findings reveal that ncRNAs-regulated TIMM8A correlates with poor prognosis of patients in breast cancer and acts as an oncogene in breast cancer." (PMID 35501914, 2022).
breast carcinoma (continued). "The HPA immunohistochemical staining database was used to show that TIMM8A protein expression was up-regulated in breast cancer tissues." (PMID 36248992, 2022). "We further verified the effect of TIMM8A on the proliferation of breast cancer cells using EdU assay." (PMID 35501914, 2022). "Based on univariate and multivariate Cox regression analyses, TIMM8A was identified as an independent prognostic factor for breast cancer." (PMID 35501914, 2022). "We further demonstrated that TIMM8A was expressed higher in breast cancer tissues than normal tissues of patients via detecting TIMM8A mRNA from total of 40 samples." (PMID 35501914, 2022). "This suggests that TIMM8A could serve as a prognostic biomarker and a potential therapeutic target in breast cancer." (PMID 40597358, 2025). "Interestingly, TIMM8A overexpression correlates with poor prognosis in breast cancer, with patients showing significantly lower overall survival compared to those with low expression." (PMID 40597358, 2025). "Taking together, hsa-circ-0107314/hsa-circ-0021867/hsa-circ-0122013 might be the three most potential upstream circRNAs of hsa-miR-34c-5p/hsa-miR-449a-TIMM8A axis in breast cancer." (PMID 35501914, 2022). "In our research, we revealed the functions of TIMM8A in breast cancer." (PMID 35501914, 2022). "All data demonstrate that TIMM8A might be a potential prognostic indicator and treatment targets for breast cancer patients." (PMID 35501914, 2022). "Moreover, TIMM8A expression was also significantly correlated with the clinical characteristics of the patients with breast cancer, including clinical stage, T category, distant metastasis." (PMID 35501914, 2022). "TIMM8A promotes proliferation of breast cancer cells in vitro and tumor growth in vivo." (PMID 35501914, 2022). "hsa-circ-0107314/hsa-circ-0021867/hsa-circ-0122013 might be the three most potential upstream circRNAs of hsa-miR-34c-5p/hsa-miR-449a-TIMM8A axis in breast cancer." (PMID 35501914, 2022). "Finally, we explored the biological functions of TIMM8A in breast cancer cell lines (MCF7 and MDA-MB-231) and patient-derived tumor fragment platform." (PMID 35501914, 2022). "In addition, IHC results showed that Ki67 levels in tumors decreased and TUNEL levels in tumors increased after TIMM8A inhibitors were administered, which further indicates that TIMM8A inhibition can suppress the proliferation and growth of breast cancer." (PMID 35501914, 2022). "In summary, these results indicated that TIMM8A was related to hormone levels, age, T phase, os events, and further suggested that TIMM8A might be a biomarker of poor prognosis for breast cancer." (PMID 36248992, 2022). "The percentage of TIMM8A genetic alteration among breast cancer patients is 0.68% (74/10950)." (PMID 35501914, 2022). "Similarly, silencing TIMM8A inhibits tumor growth in the breast cancer PDX mouse model." (PMID 35501914, 2022). "Recent studies have identified overexpression of TIMM8A and TIMM13 in various tumor types, including breast cancer, endometrial carcinoma, osteosarcoma, and cutaneous melanoma." (PMID 40918471, 2025). "We selected different types of breast cancer cell lines (MDA-MB-231 and MCF7) as representatives to explore the function of TIMM8A." (PMID 35501914, 2022). "The unpaired data analysis showed that the mRNA expression level of TIMM8A in breast cancer tissues (n = 1109) was significantly higher than that in normal tissues (n = 113) (3.391 soil 0.636 vs 3.005 soil 0.618, Mann -Whitney U-test, P < 0.001)." (PMID 36248992, 2022). "However, the biological behaviors and molecular mechanisms of TIMM8A in breast cancer remain not fully illustrated." (PMID 35501914, 2022).
Hearing impairment (5 papers, 2010 to 2022). A decreased magnitude of the sensory perception of sound. "Both neurological dysfunctions of hearing impairment and unstable gait are often thought to be due to B cell deficiencies rather than neuronopathy in auditory brain stem responses caused by the loss of TIMM8A in mitochondrial dysfunction." (PMID 33013854, 2020).